AHNAK (AHNAK nucleoprotein)
Diseases named in the same sentence as AHNAK in open-access papers (continued):
Sharing a sentence is not in itself a finding about the gene and the disease.
liver disease (4 papers, 2018 to 2023). "In order to confirm the association of STAP1 and AHNAK with liver diseases, we further analyzed the AHNAK and STAP1 methylation levels in the different types of liver cirrhosis or HCC using the GEO datasets." (PMID 36713363, 2022). "Our previous study has reported that the promoter methylation level of AHNAK gene in peripheral blood mononuclear cells (PBMC) was associated with the increase of the severity of liver diseases, and AHNAK can be employed as an early diagnostic marker for HCC." (PMID 36713363, 2022). "Our results revealed that AHNAK methylation level in peripheral blood decreases with the progression of hepatitis B‐related liver disease." (PMID 30259695, 2018). "We also evaluated the differences and changes of methylation and expression of AHNAK and STAP1 at different stages of liver disease using the TCGA and GEO public datasets." (PMID 36713363, 2022). "In order to understand the relationship between AHNAK methylation level and the progression of HBV related liver disease, we analyzed the methylation level in PBMC and T cells in different course samples." (PMID 30259695, 2018). "The promoter methylation level of AHNAK gene in PBMCs decreased with the progression of HBV‐related liver disease, and showed significant difference among the patients with various HBV‐related liver diseases (P = 0.0001)." (PMID 30259695, 2018). "Therefore, this study utilizes bioinformatics to analyze the sequencing data from previous studies to identify the relationship of AHNAK methylation with the progression and immune‐related signaling pathways of HBV‐related liver diseases." (PMID 30259695, 2018).
rhabdomyosarcoma (4 papers, 2021 to 2025). A rare aggressive malignant mesenchymal neoplasm arising from skeletal muscle. "This duality in Panx1 function could be influenced by tumor stage, molecular context, or interactions with specific proteins, such as AHNAK in rhabdomyosarcoma or β-catenin in melanoma." (PMID 40978734, 2025). "For instance, in rhabdomyosarcoma, Panx1 re-expression not only decreased cell viability, inhibited migration, and promoted apoptosis, but also exhibited an inhibitory interaction with AHNAK, highlighting its role as a regulator of malignancy in this pediatric sarcoma." (PMID 40978734, 2025). "The correlation between AHNAK and PANX1 led to initial insights into the mechanisms by which PANX1 suppresses malignant properties in rhabdomyosarcoma." (PMID 38909013, 2024).
head and neck cancer (3 papers, 2013 to 2015). A primary or metastatic malignant neoplasm affecting the head and neck. "Using AMIDA technology we initially screened for novel tumor-associated antigens (TAAs) in sera from head and neck cancer patients and we identified AHNAK as a potential candidate (see Materials and Methods section)." (PMID 23409183, 2013). "Moreover, in head and neck cancer, FOXP3 may cooperate with the inflammation factor COX2 and with the migration/invasion factors AHNAK and cortactin to promote tumor progression." (PMID 26305693, 2015).
hepatoblastoma (3 papers, 2021 to 2023). Hepatoblastoma (HB) is a malignant hepatic tumor and is the most common pediatric liver cancer. "While AHNAK expression decreased after GATA4 knockdown, overexpression of GATA4 caused AHNAK elevation, suggesting that AHNAK upregulation may promote hepatoblastoma progression." (PMID 38033502, 2023). "GATA4 is also highly expressed in most hepatoblastomas and correlates with a mesenchymal, migratory phenotype in hepatoblastoma cells by regulating the expression of ADD3, AHNAK, and IGFBP1." (PMID 33648545, 2021).
hepatopathy (3 papers, 2018 to 2024). "The combination of methylation of STAP1 and AHNAK indeed achieved a better performance in distinguishing the different types of hepatopathy patients, which suggests the diagnostic value of STAP1." (PMID 36713363, 2022). "Although we had identified that the methylation of AHNAK was a good diagnostic marker for hepatopathy, here we speculate that there was also another marker, STAP1, whose methylation also involved in the detection of hepatopathy." (PMID 36713363, 2022). "The GEO datasets also supported that the methylation of AHNAK and STAP1 was associated with different types of hepatopathy." (PMID 36713363, 2022). "Additionally, the combination of AHNAK and STAP1 methylation in PBLs has shown potential as a diagnostic marker for HBV-related hepatopathy, and LGF2 methylation levels were found to be altered in peripheral blood cells." (PMID 38397459, 2024). "We concluded that combination of AHNAK and STAP1 methylation in peripheral blood immune cells can be used as a diagnostic marker for HBV related hepatopathy and STAP1 methylation may be a potential prognostic marker for HBV related HCC." (PMID 36713363, 2022).
Insulin resistance (3 papers, 2015 to 2024). Increased resistance towards insulin, that is, diminished effectiveness of insulin in reducing blood glucose levels. "Here, we demonstrated that AHNAK KO mice are protected against HFD-induced insulin resistance, with reduced fat accumulation." (PMID 26466345, 2015).
non-small cell lung carcinoma (3 papers, 2021 to 2024). A group of at least three distinct histological types of lung cancer, including non-small cell squamous cell carcinoma, adenocarcinoma, and large cell carcinoma. "In non-small cell lung cancer (NSCLC) tissues, UBE3C maintains cancer stemness by ubiquitinating and promoting neuroblast differentiation-associated protein AHNAK (AHNAK) degradation." (PMID 35414786, 2022). "In non small-cell lung cancer, UBE3C ubiquitinated and promoted AHNAK degradation, resulting in enhanced stemness." (PMID 34689136, 2021).
pancreatic cancer (3 papers, 2017 to 2021). "All these genes are upregulated in pancreatic cancer, and seven of them are significantly associated with unfavorable prognosis (MET, YAP1, PTPN14, EPS8, AHNAK, RALB, and AFAP1)." (PMID 34957301, 2021).
adenocarcinoma of the lung (2 papers, 2017 to 2023). "The STIP1 gene was previously found rearranged with AHNAK in adenocarcinoma of the lung; however, in that particular case STIP1 constituted the 3′ moiety of the fusion whereas in the present case it is 5′." (PMID 28186972, 2017). "However, it has also been reported that AHNAK expression was elevated during TGF-β induced epithelial mesenchymal transition in human lung adenocarcinoma A549 cells, suggesting that AHNAK may promote invasion and metastasis of Lung adenocarcinoma cells." (PMID 38033502, 2023).
asthma (2 papers, 2012 to 2014). "These analyses suggested that SNPs in the AHNAK and MS4A2 genes were indirectly associated with asthma." (PMID 22432035, 2012). "In case of the RA data set two SNPs in the AHNAK gene gave the strongest correlation with the phenotype asthma+rhinitis." (PMID 22432035, 2012). "Another interesting and novel finding of this study is the indirect but strong relevance of the SNPs in the AHNAK gene to asthma." (PMID 22432035, 2012). "The AHNAK gene, induced in allergic rhinitis patients with or without asthma, was previously associated with asthma susceptibility." (PMID 24475887, 2014). "Similarly to the SNPs in AHNAK, a SNP in the TXNDC16 gene also influenced asthma risk in interaction with rhinitis." (PMID 22432035, 2012). "We compared the gene expression levels of genes found to be relevant in asthma in the SNP analysis in sputum samples of 12 asthmatics and 9 controls using TaqMan Gene Expression Assays (FRMD6, PTGDR, PTGER2, MS4A2, AHNAK, PRPF19, TXNDC16)." (PMID 22432035, 2012).
dysferlinopathy (2 papers, 2023 to 2024). "In muscle samples from dysferlinopathy patients, both AHNAK and dysferlin levels are reduced, with AHNAK showing a notable decrease in the sarcolemma but remaining stable in blood vessels, indicating a muscle-specific reduction." (PMID 38540676, 2024). "In aged dysferlin null mice and individuals with dysferlinopathy, lack of dysferlin alters expression of many dysferlin-associated proteins including AHNAK, Annexin A2, Calpain-3, Caveolin-3 and MG53." (PMID 36653852, 2023). "AHNAK mutations could influence both LGMD2A and dysferlinopathies." (PMID 38540676, 2024).
meningioma (2 papers, 2017 to 2020). A generally slow growing tumor attached to the dura mater. "This enabled validation of peptides of several candidate biomarkers like VIM, ANXA2, AHNAK, TS101, and CLIC1 from the surgically resected meningioma tissues and control arachnoid regions." (PMID 32974197, 2020). "We earlier reported an elevation in the levels of AHNAK, Gelsolin, S100 family of proteins, and several other proteins like CKAP4 that were specific to particular grades of meningiomas." (PMID 32974197, 2020).
metastatic carcinoma (2 papers, 2016 to 2023). A carcinoma which has spread from the original site of growth to another anatomic site. "The study also found that AHNAK expression was upregulated in invasive ductal carcinoma and metastatic carcinoma compared to normal breast epithelium, with higher expression in metastatic carcinoma in particular." (PMID 38033502, 2023). "Metastatic carcinoma cells contained the highest levels of AHNAK expression, particularly at the plasma membrane." (PMID 27374178, 2016).
prostate carcinoma (2 papers, 2021 to 2023). A carcinoma that arises from epithelial cells of the prostate gland. "In castration-resistant prostate cancer (CRPC), AHNAK is a downstream target molecule of BRD4, and knockdown of AHNAK or BRD4 inhibits the migration of prostate cancer cells." (PMID 38033502, 2023). "Another study reported that AHNAK mutation rate was approximately 4.82% in prostate cancer, ranking it fourth, although it was not studied in depth." (PMID 38033502, 2023). "In prostate cancer, BRD4 regulates cell migration along with infiltration through the transcription of AHNAK." (PMID 34689136, 2021).
Salmonella Infections (2 papers, 2023). Infections with bacteria of the genus SALMONELLA. "Contrary to our expectation, Salmonella infection was also enriched in clusters 1 and 3, and thus, we reviewed the DEGs and found that only six DEGs, such as AHNAK, MAP2K1, MAPK10, ARL8B, IL6, and PFN2, were enriched after S. enterica BNCC186354 infection, but only ARL8B and PFN2 were downregulated." (PMID 36980306, 2023).
systemic lupus erythematosus (2 papers, 2023 to 2025). An autoimmune multi-organ disease typically associated with vasculopathy and autoantibody production. "AHNAK can be cleaved by the both enzymes and identified as a systemic lupus erythematosus (SLE) autoantigen, promising a new target for therapy." (PMID 38033502, 2023).
uroepithelial carcinoma (2 papers, 2020 to 2025). "It was shown that AHNAK was preferentially expressed in the nucleus of urothelial carcinoma cell." (PMID 32733809, 2020). "Additionally, AHNAK levels in urine could serve as a biomarker to differentiate between uroepithelial carcinoma and normal uroepithelial cells, which aligns with our findings." (PMID 40908816, 2025).
viral infection (2 papers, 2020 to 2024). "AHNAK has been identified as a biomarker in several, including metastatic, cancers and linked to drug resistance in cancer in association with viral infection." (PMID 32411128, 2020). "Additionally, BNIP3L was elevated in bacterial infection, potentially reflecting its role in mitophagy, while DNMT1, IFI27, SLFN5, and AHNAK were elevated in viral infection, and PABPC4 was elevated in KD." (PMID 39240972, 2024).
bladder tumor (1 paper, 2022). "Our results show that the expression of AHNAK is high in BCa nuclei and regulates oncogenesis and progression by modulating T cell responses in the bladder tumor microenvironment." (PMID 36211359, 2022).
COVID-19 (1 paper, 2022). A disease caused by infection with severe acute respiratory syndrome coronavirus 2. "Among them, S100A9, AHNAK, and CX3CR1 have been reported as potential COVID-19 biomarkers previously, and the others (TRAF3IP3 and LFNG) are closely associated with the immune and virus-related signaling pathways." (PMID 35885892, 2022). "S100A9, AHNAK, and CX3CR1 have all been identified as relevant COVID-19 biomarkers." (PMID 35885892, 2022). "Among them, S100A9, AHNAK, and CX3CR1 have been reported to be important biomarkers for COVID-19." (PMID 35885892, 2022).
dementia (1 paper, 2013). Loss of intellectual abilities interfering with an individual's social and occupational functions. "Our study also indicates a crucial role of AHNAK in processes of aging-related dementia, and we hypothesize that the Cb exploits proteins such as CEND1 or GSN to fight against neurodegeneration." (PMID 24008896, 2013).
depression (1 paper, 2021). "Constitutive AHNAK knockout mice and forebrain glutamatergic neuron-selective AHNAK knockout mice were found to have a depression-like behavioral phenotype, whereas parvalbumin interneuron-selective AHNAK knockout mice displayed an antidepressant-like behavioral phenotype." (PMID 33971621, 2021).
endometrial cancer (1 paper, 2019). Primary or metastatic malignant neoplasm involving the endometrium (mucous membrane that lines the endometrial cavity). "Conversely, Hypo-O-GlcNAcylation impaired endometrial cancer cell proliferation and wound healing, and down-regulated expression of pro-EMT genes (AHNAK, CALD1, and TGFB2)." (PMID 31080560, 2019).
gout (1 paper, 2024). A condition characterized by painful swelling of the joints, which is caused by deposition of urate crystals. "Lastly, the focus of this study was on theregulation of macrophage polarization by inhibiting AHNAK, yet the specificmechanisms underlying AHNAK regulation of macrophage polarization and otherpotential pathways in gout inflammation remain inadequately explored." (PMID 39665079, 2024). "In order to verify the crucial role of AHNAK in gout, we intervened in AHNAKexpression in mice using lentivirus carrying sh-AHNAK." (PMID 39665079, 2024). "The interventionwith colchicine and R4F-NM@F127-Col effectively reduced AHNAK expression levels inmice, modulated macrophage polarization, and ameliorated symptoms in gout-afflictedmice." (PMID 39665079, 2024). "The study found that macrophagepolarization plays a critical role in gout, and AHNAK was identified as the keygene through which colchicine affects macrophage polarization." (PMID 39665079, 2024). "By intersecting the targetproteins of colchicine, gout-related genes, and core regulatory genes ofmacrophage polarization from the scRNA-seq dataset, we identified a crucialgene, AHNAK." (PMID 39665079, 2024). "Lentiviralintervention to decrease AHNAK expression was shown to alleviate joint swellingin gout mice and regulate macrophage polarization." (PMID 39665079, 2024). "In summary, we can draw the following preliminary conclusions: Colchicine inhibitsthe polarization of macrophages toward the pro-inflammatory M1 phenotype by bindingto AHNAK protein, inducing the polarization of the anti-inflammatory M2 phenotypeand subsequently alleviating gout." (PMID 39665079, 2024).
Hepatic steatosis (1 paper, 2021). Steatosis is a term used to denote lipid accumulation within hepatocytes. "To elucidate the role of AHNAK in preventing diet-induced hepatic steatosis, we determined whether Ahnak deficiency regulates HFD-induced production and release of hepatic FGF21." (PMID 33785868, 2021). "In the present study, we examined the role of AHNAK in the regulation of hepatic lipid metabolism in diet-induced fatty liver." (PMID 33785868, 2021). "In this study, we examined the role of AHNAK in regulating hepatic lipid metabolism to prevent diet-induced fatty liver." (PMID 33785868, 2021). "To determine the potential correlation between AHNAK expression and hepatic steatosis, we examined AHNAK expression in the livers of diet-induced and genetically induced obese mice." (PMID 33785868, 2021). "Characterization of phenotypic changes in Ahnak KO mice, such as reduced hepatic steatosis, decreased adiposity, and increased energy expenditure, establishes AHNAK as a novel regulator of FGF21 in modulating hepatic fatty acid metabolism." (PMID 33785868, 2021).
Hepatitis (1 paper, 2022). Inflammation of the liver. "Therefore, in this study, we collected new patient samples to investigate the correlation between the methylation of another gene, STAP1, as well as AHNAK, and the progression of hepatitis and HCC and to assess the diagnostic effect of the combination using the genes STAP1 and AHNAK." (PMID 36713363, 2022).
Huntington disease (1 paper, 2025). Huntington disease (HD) is a rare neurodegenerative disorder of the central nervous system characterized by unwanted choreatic movements, behavioral and psychiatric disturbances and dementia. "In the nervous system, roles for AHNAK are reported in Schwann cell myelination with putative implications for neuropathies, in spinal cord regeneration, and in neurological pathology associated with Huntington's disease." (PMID 41488750, 2025).
influenza (1 paper, 2023). An acute viral infection of the respiratory tract, occurring in isolated cases, in epidemics, or in pandemics; it is caused by serologically different strains of viruses (influenzaviruses) designated A, B, and C, has a 3-day incubation period, and usually lasts for 3 to 10 days. "Whole exome sequencing (WES) data of IAV-infected patients identifies a number of genes with putative loss-of-function (pLOF) variants, including structural scaffold protein AHNAK, that are associated with severe influenza disease and significantly change in our cellular proteomic data." (PMID 37758692, 2023).
invasive ductal carcinoma (1 paper, 2016). "In contrast to normal cells, robust AHNAK expression was seen in the cytoplasm and plasma membrane of the majority of invasive ductal carcinoma cells." (PMID 27374178, 2016).
leukemia (1 paper, 2024). A malignant (clonal) hematologic disorder, involving hematopoietic stem cells and characterized by the presence of primitive or atypical myeloid or lymphoid cells in the bone marrow and the blood. "FMNL1 is a formin-related protein highly expressed in hematopoietic cells and also overexpressed in leukemias, its interaction with AHNAK induced the localization of the latter at the cell membrane thereby suggesting a potential role of both of these actors in pathogenesis." (PMID 38918490, 2024).
liver cirrhosis (1 paper, 2022). "However, in the public data, there was hyper-methylation of both AHNAK and STAP1 in liver cirrhosis and hypo-methylation both in the HCC and adjacent tissues." (PMID 36713363, 2022).
metastatic melanoma (1 paper, 2017). A melanoma that has spread from its primary site to another anatomic site. "Moreover, it was reported by Sheppard et.al, that mutations in AHNAK were common in metastatic melanoma patients and also correlated with poor outcome." (PMID 28035070, 2017).
nasopharyngeal carcinoma (1 paper, 2025). A carcinoma arising from the nasopharyngeal epithelium. "AHNAK has been reported to function as a tumor suppressor in nasopharyngeal carcinoma, where its downregulation was shown to be associated with poor overall survival." (PMID 41009656, 2025).
promyelocytic leukemia (1 paper, 2019). "Although AHNAK was originally revealed to be involved in promyelocytic leukemia, it is currently known to be related to solid tumor development." (PMID 30836988, 2019).
sarcopenia (1 paper, 2025). Progressive decline in muscle mass due to aging which results in decreased functional capacity of muscles. "Plasma AHNAK protein levels was higher in the sarcopenia group but was lower in the ESRD group." (PMID 40207397, 2025).